ENSG00000287482 (novel transcript)
Gene: Long non-coding RNA gene on chromosome 15 (25,091,786 to 25,107,469, reverse strand). Ensembl gene ENSG00000287482.
Gene Ontology:
Biological process: RNA processing
Cellular component: nucleolus